PLEK2 (pleckstrin 2)
Description:
May help orchestrate cytoskeletal arrangement. Contribute to lamellipodia formation.
Tractability: Antibody: UniProt places it where antibodies can reach, with medium confidence; its Gene Ontology location is reachable by antibodies, with medium confidence. PROTAC: ubiquitination databases record sites on it.
Gene: Protein-coding gene on chromosome 14 (67,385,652 to 67,412,176, reverse strand). Ensembl gene ENSG00000100558.
Subcellular location: Cell projection, lamellipodium membrane; Cytoplasm, cytoskeleton
Subcellular location (Human Protein Atlas): Vesicles; Cytosol
Gene Ontology:
Molecular function: phosphatidylinositol-3,4-bisphosphate binding; phosphatidylinositol-3,5-bisphosphate binding; phosphatidylinositol-3-phosphate binding
Biological process: actin cytoskeleton organization; erythrocyte enucleation; intracellular signal transduction; positive regulation of plasma membrane bounded cell projection assembly
Cellular component: plasma membrane; cytoskeleton; lamellipodium membrane; membrane
Genetic constraint (gnomAD): Loss-of-function variants: 22 observed, 33.99 expected, observed/expected ratio (o/e) 0.65, 90% interval 0.46 to 0.92. The upper end of that interval is the gene's LOEUF score, 0.92, which puts it in group 3 of 6, group 1 being the genes least tolerant of losing a copy. Missense variants: 361 observed, 412.82 expected, observed/expected ratio (o/e) 0.87, 90% interval 0.8 to 0.95. Synonymous variants: 147 observed, 158.8 expected, observed/expected ratio (o/e) 0.93, 90% interval 0.81 to 1.06.
Homologues: Orthologues: chimpanzee PLEK2 (99% identical), macaque PLEK2 (99% identical), mouse Plek2 (95% identical), pig PLEK2 (94% identical), rat Plek2 (93% identical), dog PLEK2 (93% identical), guinea pig PLEK2 (90% identical), rabbit PLEK2 (86% identical), zebrafish plek2 (58% identical). Paralogues in human: PLEK (38% identical).
Diseases named in the same sentence as PLEK2 in open-access papers:
PLEK2 is named in the same sentence as 56 diseases in open-access papers, as found by Europe PMC text mining. Sharing a sentence is not in itself a finding about the gene and the disease. The quoted sentences say what the papers report.
gallbladder cancer (7 papers, 2019 to 2024). "PLEK2 has been documented in the context of colorectal cancer, esophageal cancer, and gallbladder cancer 41-43." (PMID 38370379, 2024). "The current research on PLEK2 has focused on head and neck squamous cell carcinoma, esophageal squamous cell carcinoma, gallbladder cancer, myeloproliferative neoplasms, gastric cancer, non-small cell lung cancer, and breast cancer." (PMID 39687904, 2024). "The mechanisms of Plek2 in tumorigenesis can be tissue specific, as Plek2 is reported to promote the invasion and metastasis of gallbladder cancer through binding and activation of EGFR." (PMID 36719747, 2023). "PLEK2 also mediated vascular invasion and metastasis in non-small-cell lung cancer and gallbladder cancer." (PMID 34394345, 2021). "PLEK2 has been reported to be highly expressed in several tumor types and promotes cancer progression and metastasis, including breast cancer, gastric cancer, prostate cancer, gallbladder cancer, and non-small-cell lung cancer." (PMID 39687904, 2024). "It has been demonstrated that PLEK2 interacts with epidermal growth factor receptor (EGFR) and suppresses EGFR ubiquitination mediated by c-CBL, leading to downstream CCL2 transcriptional overexpression and EMT process activation in gallbladder cancer." (PMID 34869363, 2021).
lung carcinoma (7 papers, 2021 to 2025). "The evidence for PLEK2 in metastasis is just emerging and closely linked with TGFβ signalling in lung cancer and EGFR signalling in bladder cancer." (PMID 34592589, 2021). "Additionally, PLEK2 could promote metastasis and vascular invasion in non‐small cell lung cancer, and its overexpression might be associated with poor progression‐free survival in patients with lung adenocarcinoma." (PMID 34331382, 2021). "α5-nAChR mediates PLEK2 expression, a member of the pleckstrin protein family discovered in platelets and leukocytes, within the context of lung cancer through the regulation of STAT3." (PMID 40143965, 2025). "Nicotine interacts with α5-nAChR on the surface of lung cancer cells, activating the α5-nAChR/PLEK2 signaling pathway, which is crucial for cellular migration, invasion and differentiation." (PMID 40143965, 2025). "Meanwhile, these findings suggested that its role as a biomarker was particularly significant in certain cancers, such as lung cancer and melanoma, where high PLEK2 levels correlate strongly with poorer clinical outcomes and reduced immunotherapy response." (PMID 39546161, 2024). "Silencing of PLEK2 was shown to reduce proliferative and migrated ability of lung cancer cells via prohibition of autophagy." (PMID 37910672, 2023). "Second, more in vivo and vitro experiments are needed to deeply investigate the biological effects of PLEK2 in lung cancer." (PMID 37910672, 2023). "Four key genes can serve as molecular targets for patients with LUAD; silencing of PLEK2 was shown to reduce proliferative and migrated ability of lung cancer cells via prohibition of autophagy." (PMID 37910672, 2023). "Consistent with our results, other PSMC signature-related genes, including LDHA, SEC61G, PLEK2, and C1QTNF6, have been shown to be risk genes in lung cancer in vitro, mediating the development, growth, and metastasis of lung cancer." (PMID 36699466, 2022). "The function and prognosis of PLEK2 in lung cancer have been reported previously." (PMID 34331382, 2021). "As expected, the silencing of these genes inhibited lung cancer cell proliferation and growth (B3GNT3, GALNT7, PLEK2)." (PMID 35211471, 2022). "Four genes (C1QTNF6, DLGAP5, HMMR, and PLEK2) were identified as key genes in LUAD progression, which were upregulated in the cancerous tissue compared with in the normal tissue (P < 0.001), and correlated with an unwanted prognosis in lung cancer (P < 0.05)." (PMID 37910672, 2023).
pancreatic cancer (6 papers, 2021 to 2025). "Consistently, PLEK2 had been proven to play roles in the proliferation of pancreatic cancer stem cells." (PMID 40682666, 2025). "Recent studies have found that pancreatic cancer tissues exhibited an enhancement of PLEK2 expression." (PMID 34394345, 2021). "Similarly, miR-873, which was shown to be downregulated in pancreatic cancer and inhibits PLEK2 mRNA via the pleckstrin-2-dependent PI3K/AKT pathway, is associated with better survival." (PMID 37686149, 2023). "Similarly, PI3K/AKT signaling mediated by PLEK2 is also involved in osteosarcoma tumorigenesis and metastasis and in self-renewal and proliferation of pancreatic cancer stem cells." (PMID 34869363, 2021). "PLEK2 could promote the self-renewal and proliferation of pancreatic cancer stem cells." (PMID 34394345, 2021). "Downregulation of PLEK2 by miRNA displayed inhibited the PI3K/AKT pathway and self-renewal in pancreatic cancer stem cells and promoted apoptosis." (PMID 37779898, 2023).
colorectal cancer (5 papers, 2022 to 2025). A primary or metastatic malignant neoplasm that affects the colon or rectum. "The pleckstrin 2 gene (PLEK2) encodes a membrane‐bound phosphatidylinositol generated by phosphatidylinositol 3‐kinase; this gene is a canonical downstream effector of KRAS activation, and its overexpression has been associated with colorectal cancer." (PMID 40013338, 2025). "Our analysis revealed that Plek2 expression levels were indicative of how mouse models of 4T1, T22 (mammary cancer), and CT26 (colorectal carcinoma) responded to immunotherapy treatments targeting PD-L1 and CTLA-4." (PMID 39546161, 2024).
melanoma (5 papers, 2011 to 2024). A malignant, usually aggressive tumor composed of atypical, neoplastic melanocytes. "Meanwhile, a comprehensive transcriptome analysis of whole blood identified PLEK2 as the most effective gene for differentiating CD45-subtype melanoma patients from the healthy population." (PMID 39687904, 2024). "PLEK2 has been found to be overexpressed in the blood of melanoma patients in all stages of disease, suggesting its potential function as a liquid biopsy marker for early diagnosis." (PMID 34394345, 2021). "Meanwhile, a large whole blood-based transcriptome analysis identified PLEK2 expression was the strongest gene to distinguish CD45− subsets melanoma patients from healthy people." (PMID 31182136, 2019). "PLEK2 expression in CD45− cells was over 3-fold higher in melanoma patients compared with healthy individuals." (PMID 21698244, 2011). "Further analysis of C1QB, PLEK2 and the other validated biomarkers in fractionated blood cells will provide us more insight into their functions and roles in melanoma development and progression." (PMID 21698244, 2011). "In particular, PLEK2, the strongest gene to classify melanoma patients, was expressed in CD45− subsets, illustrating the importance of analyzing whole blood cells for biomarker studies." (PMID 21698244, 2011). "Although sample numbers from each stage were small (n = 3 to 8), upregulation of PLEK2 expression in CD45− subset was detected in blood samples of all stages of melanoma patients." (PMID 21698244, 2011). "The expression of PLEK2, the strongest gene to classify melanoma patients, in CD45− subsets illustrates the importance of analyzing whole blood cells for biomarker studies." (PMID 21698244, 2011). "Transcriptome profiling of PLEK2 expression in whole blood cells could be used as early detection of melanoma." (PMID 31182136, 2019). "Indeed, PLEK2 as a single gene model, allowed 42/50 (84%) controls and 38/45 (86.7%) melanoma patients to be classified accurately." (PMID 21698244, 2011). "It is thus tempting to consider that increased expression of PLEK2 in blood cells of melanoma patients may provide an environment for tumor growth and metastasis by inducing the production of lamellipodia in circulating cells." (PMID 21698244, 2011). "Consequently, PLEK2 can be utilized for the early detection of melanoma." (PMID 39687904, 2024). "Of these, a 2-gene signature consisting of PLEK2 and C1QB led to the best result that correctly classified 93.3% melanoma patients and 90% healthy controls." (PMID 21698244, 2011). "We then compared expression of PLEK2 in CD45− cells and that of CIQB in CD45+ cells using blood samples from 20 melanoma patients and 20 healthy control individuals by standard qRT-PCR analysis." (PMID 21698244, 2011). "It is possible that PLEK2 and C1QB may belong to independent pathways; therefore, changes in expression of both genes may increase reliability in detecting melanoma patients." (PMID 21698244, 2011).
non-small cell lung carcinoma (5 papers, 2021 to 2025). A group of at least three distinct histological types of lung cancer, including non-small cell squamous cell carcinoma, adenocarcinoma, and large cell carcinoma. "Similarly, elevated PLEK2 expression has been associated with enhanced invasion and metastasis in multiple cancers, including gallbladder cancer, non-small cell lung cancer, breast cancer, and head and neck squamous cell carcinoma (HNSCC)." (PMID 39546161, 2024). "The mechanisms of PLEK2 in tumorigenesis is tissue specific, as PLEK2 mediates proliferation and metastasis in non-small cell lung cancer via SHIP2/PI3K/AKT and bromodomain containing protein 4 expression." (PMID 40682666, 2025). "A study reported that PLEK2 was highly expressed in non-small cell lung cancer cells and promoted EMT, EndoMT, vascular endothelial barrier disruption, and tumor metastasis, suggesting the role of PLEK2 in tumor metastasis." (PMID 39687904, 2024). "In our in vitro experiments, we used three non-small cell lung cancer (NSCLC) cell lines to confirm that PLEK2 knockdown significantly inhibited tumor cell growth and migration." (PMID 39546161, 2024). "Previous studies reported that PLEK2 mRNA was upregulated in non-small-cell lung cancer cells with TGF-β-induced EMT, demonstrating the crucial role of PLEK2 in tumour invasion." (PMID 34394345, 2021). "Additionally, PLEK2 expression is upregulated by TGF−β stimulation through ELK1 and Smad2/3 in non-small cell lung cancer and esophageal squamous cell carcinoma, respectively." (PMID 34869363, 2021).
breast carcinoma (4 papers, 2019 to 2025). "This is all in line with findings that pleckstrin-2-promoted PPM1B degradation plays an important role in transforming growth factor-β-induced breast cancer cell invasion and metastasis." (PMID 41301499, 2025). "A study showed PLEK2 expression was positively correlated with luminal A type breast cancer cells disseminating to bone marrow." (PMID 31182136, 2019). "Additionally, analysis of cancer cell lines indicated elevated PLEK2 expression in specific cancer types, such as malignant neoplasms of the digestive system, bladder, head and neck, cervix, thyroid, lung, pleural mesothelioma, and breast cancer." (PMID 39546161, 2024).
esophageal cancer (4 papers, 2021 to 2024). A primary or metastatic malignant neoplasm involving the esophagus. "In previous studies, we found that PLEK2 knockdown inhibited proliferation and migration in esophageal cancer cells via the AKT pathway." (PMID 39546161, 2024). "Mechanistically, our previous research in esophageal cancer cells confirmed that PLEK2 knockdown inhibited tumor growth and metastasis by suppressing the AKT pathway." (PMID 39546161, 2024). "Most have previously been proposed as biomarkers in a specific tumor (or tumor-related condition): C15orf48 in esophageal cancer, NF2 in neurofibromatosis, CMTM6 in renal adenocarcinoma, PLEK2 in lung adenocarcinoma, RRM2 in glioma, HOXA1 in breast and gastric cancers, and SAA2 in renal cancer." (PMID 34204789, 2021).
gastric cancer (4 papers, 2021 to 2024). A primary or metastatic malignant neoplasm involving the stomach. "We detected that PLEK2 overexpression in gastric cancer was associated with shorter survival time." (PMID 34394345, 2021). "We further determined the relationship between PLEK2 mRNA and the overall survival of gastric cancer patients based on the web-based database Kaplan-Meier plotter." (PMID 34394345, 2021). "To explore the effect of PLEK2 in human gastric cancer, we established stable PLEK2 knockdown models in MGC803 and SGC7901 cells by expressing short hairpin RNAs (shPLEK2)." (PMID 34394345, 2021). "Survival analysis was utilized to test the clinical impacts of the levels of PLEK2 in gastric cancer patients." (PMID 34394345, 2021). "Kaplan-Meier plotter analysis revealed that gastric cancer patients with higher PLEK2 levels had substantially poorer overall survival compared with gastric cancer patients with lower PLEK2 levels." (PMID 34394345, 2021). "Then, we evaluated the expression of PLEK2 by IHC staining in clinical gastric cancer tissues and found high expression in 46 cases (42.6%) and low expression in the other 62 cases (57.4%)." (PMID 34394345, 2021). "As expected, the upregulation of PLEK2 accelerated gastric cancer cell proliferation in the MTT assay." (PMID 34394345, 2021). "The overexpression of PLEK2 significantly improved gastric cancer cell migration in a Transwell assay." (PMID 34394345, 2021). "In this study, PLEK2 expression was evaluated in The Cancer Genome Atlas (TCGA) datasets and clinical gastric cancer samples using real-time PCR, western blotting, and immunohistochemistry (IHC)." (PMID 34394345, 2021). "To date, the expression of PLEK2 and its role in gastric cancer progression and pathogenesis are still elusive." (PMID 34394345, 2021). "In vitro and in vivo studies were used to estimate the potential roles played by PLEK2 in modulating gastric cancer proliferation, self-renewal, and tumourigenicity." (PMID 34394345, 2021). "Western blotting illustrated that the expression of PLEK2 was stronger in gastric cancer tissues than in the peritumoural gastric tissues." (PMID 34394345, 2021). "We found that PLEK2 was preferentially accumulated in gastric cancer tissues and probably enhanced the EMT mechanism." (PMID 34394345, 2021). "The upregulation or downregulation of PLEK2 in gastric cancer cell lines effectively enhanced or inhibited cell proliferation and proinvasive behaviour, respectively." (PMID 34394345, 2021). "We found that PLEK2 was remarkably upregulated in the RNA-seq dataset of 444 gastric cancer samples." (PMID 34394345, 2021). "We employed a nude mouse tumourigenicity assay to detect the functional roles of PLEK2 in gastric cancer tumourigenicity." (PMID 34394345, 2021). "In this research, we studied the effect of PLEK2 in gastric cancer utilizing survival analysis, cell test in vitro, and nude mouse experiment in vivo." (PMID 34394345, 2021). "In this study, we confirmed the role of PLEK2 in promoting EMT in gastric cancer cells." (PMID 34394345, 2021). "PLEK2 expression in gastric cancer was examined by western blotting and real-time PCR." (PMID 34394345, 2021). "PLEK2 upregulation in gastric cancer cells increased cell migration, invasion, proliferation, and self-renewal in vitro and tumourigenesis in vivo, indicating that PLEK2 may have an oncogenic function in gastric cancer." (PMID 34394345, 2021). "Overall, our findings indicate that PLEK2 is a potential prognostic indicator and employed by self-renewal and proliferation which may provide a better understanding of gastric cancer tumourigenesis." (PMID 34394345, 2021). "We upregulated PLEK2 expression in gastric cancer cells to determine its effects." (PMID 34394345, 2021). "The results showed that PLEK2 promoted EMT in gastric cancer cells." (PMID 34394345, 2021). "Our findings demonstrated that PLEK2 plays a potential role in gastric cancer and may be a novel therapeutic target for gastric cancer." (PMID 34394345, 2021).
gastric cancer (continued). "In summary, we discovered that PLEK2 was remarkably elevated in gastric cancer." (PMID 34394345, 2021). "Our research also revealed the key functions of PLEK2 in promoting gastric cancer epithelial-mesenchymal transition (EMT), which may have implications for gastric cancer metastasis." (PMID 34394345, 2021). "Our work suggests that targeting PLEK2 might be an effective therapeutic strategy to treat PLEK2-high gastric cancer." (PMID 34394345, 2021). "The overexpression of PLEK2 significantly promoted gastric cancer cell colony-forming abilities." (PMID 34394345, 2021). "The knockdown of PLEK2 significantly inhibited gastric cancer cell colony-forming abilities." (PMID 34394345, 2021). "Collectively, the results showed that PLEK2 may serve as an oncogene that enhances gastric cancer proliferation." (PMID 34394345, 2021). "In addition, recent findings suggest a potential relationship between PLEK2 expression and immune cell infiltration in the tumor microenvironment, particularly in gastric cancer (GC) and ESCC." (PMID 39546161, 2024). "However, the potential roles of PLEK2 in gastric cancer are still unknown." (PMID 34394345, 2021). "Western blotting and real-time PCR analysis also revealed that gastric cancer cell lines, including BGC-823, MGC-803, MKN45, SGC-7901, and AGS, exhibited high PLEK2 protein and mRNA expression." (PMID 34394345, 2021). "PLEK2 expression was significantly upregulated in gastric cancer as compared with nontumour samples." (PMID 34394345, 2021).
glioblastoma (4 papers, 2021 to 2025). The most malignant astrocytic tumor (WHO grade IV). "The greatest differences appear between glioblastoma and other gliomas (particularly in relation to tumor grade G4 vs. G3/G2), where GCSH and PLEK2 can be used to distinguish them since they exhibit opposite expression profiles in this regard." (PMID 34204789, 2021). "Together with the already described glioma biomarker, RRM2, we considered PLEK2 and GCSH as a novel WWOX-dependent biomarker triad of glioblastoma, whose subsequent investigation is advisable." (PMID 34204789, 2021).